ENSG00000269693 (novel transcript)
Gene: Protein-coding gene on chromosome 19 (12,525,720 to 12,580,975, reverse strand). Ensembl gene ENSG00000269693.
Genetic constraint (gnomAD): Missense variants: 149 observed, 202.65 expected, observed/expected ratio (o/e) 0.74, 90% interval 0.64 to 0.84. Synonymous variants: 64 observed, 68.28 expected, observed/expected ratio (o/e) 0.94, 90% interval 0.76 to 1.15.